LGALS3 (galectin 3)
Diseases named in the same sentence as LGALS3 in open-access papers (continued):
Sharing a sentence is not in itself a finding about the gene and the disease.
pancreatic cancer (continued). "Neither high expression of galectins nor galectin-3 in pancreatic cancer were associated with clinical characteristics." (PMID 31832021, 2019). "Silencing of galectin-3 decreased pancreatic cancer cell proliferation and cyclin-D1 levels." (PMID 31832021, 2019). "However, on the contrary to our data, galectin-3 silencing alone by siRNA was sufficient to induce apoptosis of the pancreatic cancer cells as well as to inhibit proliferation of SK-OV-3 and OVCRA429 ovarian cancer cells." (PMID 30585294, 2019). "However, fluorescence microscopy revealed comparatively lesser expression level of galectin-3 in the pancreatic tumor." (PMID 27382435, 2016). "The interaction of CD176 on circulating cancer cells and Galectin-3 expressed on the endothelium of distant organ vessels were found to mediate the initial, rate-limiting stages of hematogenous metastasis in several cancer entities, including breast, prostate, colon and pancreatic carcinomas." (PMID 37915564, 2023). "Galectin-3 (Gal-3), an endogenous lectin, helps stabilize MUC4 mRNA in the cytoplasm, which is highly expressed in pancreatic cancer cells." (PMID 40699805, 2025). "Increased β3, by interacting with galectin-3, thus activating KRAS, RELB, and NF-ΚB pathways, is involved in erlotinib and lapatinib resistance in lung cancer and linsitinib resistance in pancreatic cancer." (PMID 39063187, 2024). "A preclinical study has reported successful outcomes with antibody therapy targeting galectin-3 in pancreatic cancers via EGFR, indicating that galectin-3 blockade reduced tumor cell migration, adhesion, and invasion." (PMID 39451592, 2024). "Recently, we involved the carbohydrate-binding protein Galectin-3 (Gal-3) as a druggable target for KRAS-mutant-addicted lung and pancreatic cancers." (PMID 34112916, 2021). "As a novel galectin-3 inhibitor, HH1-1 exerts antitumor activity against pancreatic cancer by blocking the galectin-3/EGFR/AKT/FOXO3 signaling pathway." (PMID 34744747, 2021). "Another study has indicated that the use of galectin-3 inhibitors can block the binding of galectin-3 to EGFR, thus inhibit the galectin-3/EGFR/Akt/FOXO3 axis and inhibit the occurrence and development of pancreatic cancer in vivo and in vitro." (PMID 30996686, 2019). "Therefore, although elevated galectin-3 has been observed in pancreatic cancer patients, galectin-3 alone might not be a viable diagnostic marker of pancreatic cancer due to its role in inflammatory diseases." (PMID 31832021, 2019). "Additionally, biomarkers such as AFP, CD44, Galectin-3, and CEA exhibit notable importance, reinforcing their relevance in pancreatic cancer detection." (PMID 40217526, 2025). "Specifically, galectin-3 is not detected in normal pancreatic organs but is highly expressed in pancreatic cancer patients." (PMID 36428567, 2022). "Our mechanism derived biomarkers (HIF-1α and galectin-3) suggest the evaluation of Hsp90 inhibitors in pancreatic cancer, and not just in kinase-addicted cancers." (PMID 33672199, 2021). "The controversial role of galectin-3 in prognosis has been addressed in numerous studies, our present study indicated that galectin-3 showed limited prognostic value, with no direct correlation to OS and clinical characteristics in pancreatic cancer." (PMID 31832021, 2019). "As expected, in the pancreatic tumor, MUC16 colocalizes with galectin-3." (PMID 27382435, 2016). "al. studied a variety of pancreatic cell lines in vitro and in vivo (subcutaneous xenografts) after manipulation of galectin-3 levels and concluded that galectin-3 had no consistant oncogenic function in pancreatic cancer cells." (PMID 22900040, 2012). "Regarding the mitochondrial function, our data demonstrated a more efficient OXPHOS in the absence of Galectin-3, and especially a higher activity of complex I (NADH oxidase) and complex IV (cytochrome C oxidase) in pancreatic cancer cells." (PMID 32398681, 2020).
lung carcinoma (57 papers, 1999 to 2025). "For instance, overexpression of galectin-3 in lung cancer cells was found to be associated with increased resistance to apoptosis compared with that of non-transfected control cells." (PMID 25373317, 2015). "Galectin-3 plays a central role in lung cancer progression by regulating tumor cell proliferation, immune evasion, and angiogenesis." (PMID 40935640, 2025). "In vivo, combination therapy with TREM2 knockout and the galectin-3 inhibitor GB1107 substantially inhibited lung cancer progression." (PMID 39135069, 2024). "In our study, we have analyzed galectin-1, galectin-3, and galectin-9, as these are among the most extensively studied galectins in the context of lung cancer." (PMID 38539500, 2024). "Our research builds upon previous studies examining the alterations in galectin-3 levels in lung cancer." (PMID 38539500, 2024). "Among these secreted proteins, galectin-3 exhibits high expression levels in non-small cell lung cancer (NSCLC), and galectin-3 deficiency or pharmacological blockade significantly inhibits lung cancer progression." (PMID 39135069, 2024). "The interaction between TREM2 and galectin-3 was also confirmed in F4/80+ macrophages from patients with lung cancer using endogenous CO-IP experiments." (PMID 39135069, 2024). "Genetic and pharmacological blockade of TREM2 and galectin-3 significantly inhibited lung cancer progression in subcutaneous and orthotopic cancer models by remodeling the tumor immune microenvironment." (PMID 39135069, 2024). "Published reports have demonstrated both LGALS3 expression and binding capacity as independent poor prognostic markers in lung cancer patients, and treatment with an LGALS3 inhibitor was sufficient to reduce NSCLC tumor growth and metastasis in murine models." (PMID 35708914, 2022). "For example, FOXD1 is overexpressed in lung cancer and activate galectin-3/LGALS3 expression to promote lung cancer aggressiveness." (PMID 34028536, 2021). "Galectin-3 is the only chimera-type galectin and was increased in all stages of breast, colon, and lung cancer." (PMID 34638303, 2021). "Galectin-3 activates TLR4 signaling thus affecting lung cancer cell proliferation and migration through TLR4/NF-κB/NEAT1." (PMID 29788922, 2018). "Previously, it was reported that EGFR-dependent SOX2 expression or β-catenin activation by galectin-3 regulates lung cancer stem cells." (PMID 27626163, 2016). "Higher levels of both galectin-3 and β-catenin in poorly differentiated and advanced stages of lung cancer were noted." (PMID 25669973, 2015). "There is a correlation among the expression of galectin-3/β-catenin, lung cancer progression, and stemness." (PMID 25669973, 2015). "It has been shown that galectin-3 expression is increased in patients with breast, gastrointestinal, or lung cancer." (PMID 23265237, 2012). "Compared with healthy individuals, serum levels of galectin-3 in patients with lung cancer were significantly elevated." (PMID 23658855, 2010). "Notably, combination therapy with TREM2 knockout and the galectin-3 inhibitor GB1107 substantially inhibited lung cancer progression in vivo by decreasing tumor-infiltrating M2-like macrophages and increasing antitumor CD8+ T and NK cells." (PMID 39135069, 2024). "Notwithstanding, the mechanism by which galectin-3 levels vary among histological subtype of lung cancer remains unknown and is a limitation of this exploratory study." (PMID 38539500, 2024). "Immunohistochemical analyses demonstrated a high expression of galectin-3 in lung cancer." (PMID 39135069, 2024). "ELISA results demonstrated a significant increase in the protein level of galectin-3 in lung cancer compared to normal lung, indicating that galectin-3 may have a crucial regulatory function in the progression of lung cancer." (PMID 39135069, 2024).
lung carcinoma (continued). "Galectin-3 can promote macrophage differentiation to an M2-like phenotype and inhibit CD8+ T cell-mediated anti-tumor effects; therefore, galectin-3 deficiency or pharmacological blockade can significantly inhibit lung cancer progression." (PMID 39135069, 2024). "Furthermore, the galectin-3-EGFR complex promotes lung cancer stemness by activating downstream signaling and upregulating Sox-2 expression via c-Myc." (PMID 36823664, 2023). "Further studies are necessary to understand the role of galectin-3 in activating basophils, and how IL-4/IL-13 and other mediators could contribute to human and experimental lung cancer." (PMID 36578500, 2022). "Although Puthenedam’s report showed that MMP7-cleaved galectin-3 inhibited the motility of intestinal epithelial cells, there was no further evidence indicating the phenomena could be applied to lung cancer cells." (PMID 30925742, 2019). "Given that Galactin-3 positively regulates TLR4 protein expression, as well as the proliferation and migration of lung cancer cell lines; next, we investigated whether Galectin-3 acts through TLR4/NF-κB/NEAT1." (PMID 29788922, 2018). "The overexpression of Galectin-3 has been observed in lung cancer." (PMID 29788922, 2018). "Similarly to galectin-3, galectin-1 has recently been identified to promote lung cancer metastasis by potentiating integrin α6β4 and Notch1/Jagged2 signaling." (PMID 28860622, 2017). "Notably, the overexpression of galectin-3 in A549 lung cancer cells, which have low capability to grow as tumor spheres, promoted CSC formation." (PMID 25669973, 2015). "Targeting galectin-3 signaling may provide a new strategy for lung cancer treatment by inhibiting stem-like properties." (PMID 25669973, 2015). "A positive correlation between galectin-3 and β-catenin was found in lung cancer tissues." (PMID 25669973, 2015). "Galectin-3/β-catenin may be a novel mechanism contributing to the initiation and maintenance of lung CSCs, suggesting that targeting galectin-3 may provide an innovative strategy worth considering for lung cancer therapy." (PMID 25669973, 2015). "The expression of galectin-3 robustly increased in lung cancer spheres over serial passages, but its suppression in the H1299 monolayer or spheres resulted in reduced expression of stemness-related genes, sphere-forming ability, tumorigenicity, chemoresistance, and tumor initiation in mice." (PMID 25669973, 2015). "More specifically, most galectin-3 and β-catenin coexpressed lung tissues (n = 106) expressed CD133 (n = 86), suggesting that galectin-3/β-catenin were associated with the stem-like properties of lung cancer." (PMID 25669973, 2015). "Targeting galectin-3 may improve clinical outcomes for lung cancer patients by overcoming chemoresistance." (PMID 25669973, 2015). "All these findings show that galectin-1, galectin-3, and galectin-8 are the most abundantly expressed galectins while the expression of galectin-4, galectin-7, and galectin-9 is relatively low, both in tumor tissues and in different lung cancer cell lines." (PMID 25259711, 2014). "Galectin-3 may be useful in lung cancer diagnosis and may increase diagnosis rate when combined with other lung cancer markers." (PMID 23945245, 2013). "However the number of studies, which evaluated correlations between galectin-3 and cyclin D1 expression is limited and we didn't find any studies performed in lung cancer tissue." (PMID 22024187, 2011). "All together these data suggest that galectin-3 can be a reliable marker for lung cancer." (PMID 23658855, 2010). "Additionally, it may provide an explanation for why galectin-3 is elevated in adenocarcinoma compared to other types of lung cancer." (PMID 38539500, 2024). "Galectin-3 may be a potential marker of prognosis and a novel target for lung cancer therapy." (PMID 25669973, 2015).
lung carcinoma (continued). "This has been demonstrated by galectin-3 and the transcription factor FOXD1 forming a positive feedback loop through the ERK intracellular signaling pathway, which promotes lung cancer aggressiveness." (PMID 38927753, 2024). "The present study aims to analyze the role of galectin‐3 (GAL‐3) in the lung tumor microenvironment (TME) using tumorspheres as a model and explore its potential role as a predictive and prognostic biomarker in non‐small cell lung cancer patients." (PMID 37567864, 2024). "Of note, only certain KRAS mutant lung cancers (those expressing both galectin-3 and integrin αvβ3) rely on a process of anchorage-independent growth, showing the close relationship between membrane signaling and KRAS dependence in lung cancer." (PMID 35406400, 2022). "Based on microarray analysis, we identified galectin-3/LGALS3 (Gal-3) as a potential downstream target of FOXD1, as FOXD1 transactivated Gal-3 by interacting with the Gal-3 promoter to upregulate Gal-3 in FOXD1-overexpressing CL1-0 lung cancer cells." (PMID 31795213, 2019). "We revealed that Galectin-3-induced TLR4 signaling activation is involved in miR-548c regulation of lung cancer cell proliferation (data not shown)." (PMID 29788922, 2018). "Herein, we hypothesized that Galectin-3 may activate TLR4/NF-κB/NEAT1, thereby affecting lung cancer cell proliferation and migration." (PMID 29788922, 2018). "Furthermore, galectin-3 expression correlated with tumor progression and expressions of β-catenin and CSC marker CD133 in lung cancer tissues." (PMID 25669973, 2015). "Doxorubicin is not routinely utilized in the treatment of lung cancer; therefore, this may explain why we observed a difference in galectin-3 levels in our study." (PMID 38539500, 2024). "Notably, TREM2 knockout combined with the galectin-3 inhibitor GB1107 substantially inhibited the immunosuppressive effect of M2-TAMs and enhanced T/NK cell-mediated anti-tumor effects, improving the efficacy of lung cancer therapy." (PMID 39135069, 2024). "Moreover, the cell proliferation and migration of lung cancer cell were significantly suppressed by Galectin-3 knockdown while promoted by Galectin-3 overexpression, indicating the potential role of Galectin-3 in activating TLR4 signaling and promoting lung cancer progression." (PMID 29788922, 2018). "Therefore, circulating values of galectin-3 may represent a sensitive but nonspecific test in diagnosing breast, colon, or lung cancer." (PMID 34638303, 2021). "However, the effect of galectin-3 on stemness of lung cancer has not been determined." (PMID 25669973, 2015). "Protease secretion by lung carcinoma cell lines could not be inhibited by lactose and V14, two ERC antagonists, or by blocking antibodies against αVβ3 integrin and galectin-3." (PMID 29707150, 2018).
chronic heart failure (54 papers, 2011 to 2026). "Considering the inflammatory nature of IBD and established association of galectin-3 with different pathological conditions including chronic heart failure, further studies should also include a second control group." (PMID 41226478, 2025). "In this study, we measured NT-proBNP, a widely utilized and well-validated biomarker of congestive heart failure, and two novel protein markers of fibrosis recently found to be associated with SSc, periostin and galectin-3." (PMID 40743121, 2025). "The search strategy included a combination of Medical Subject Headings (MeSH) terms and free-text keywords related to "galectin-3", "chronic heart failure", "mortality", "prognosis", and "risk stratification"." (PMID 40734851, 2025). "Circulating galectin-3 has emerged as a valuable marker for risk stratification and prognostic evaluation of patients with congestive heart failure unrelated to SSc." (PMID 40743121, 2025). "As the galectin-3 level increases, all-cause mortality also increases by 1.1- to 2.17-fold in patients with acute or chronic heart failure, DM, or CKD and even the general population." (PMID 34437403, 2021). "To date, this is the first study to explore an association between changes in galectin-3 plasma levels and response to stem cell therapy in patients with chronic heart failure." (PMID 31885743, 2019). "Plasma galectin-3 was elevated in patients with chronic heart failure and high plasma galectin-3 level was associated with renal insufficiency." (PMID 27089335, 2016). "In patients with an eGFR <60 mL/min per 1.73 m2, galectin-3 concentration was also associated with myocardial infarction and death due to chronic heart failure." (PMID 27089335, 2016). "In the 2017 ACC/AHA guidelines for risk stratification in patients with chronic heart failure, novel markers of myocardial remodeling [soluble suppression of tumorigenesis 2 (sST2) and galectin-3 (Gal-3)] were given a class IIb recommendation for use in clinical practice." (PMID 40336640, 2025). "Additionally, the DEAL-HF study demonstrated the prognostic value of galectin-3 in chronic heart failure patients, where higher levels were associated with worse outcomes, further underscoring its significance in cardiac fibrosis." (PMID 39063659, 2024). "Increased levels of galectin-3 were observed to be a strong interpreter of death in cases of acute heart failure, including both forms of chronic heart failure." (PMID 39129285, 2025). "Galectin-3, a regulatory protein, is elevated in both acute and chronic heart failure and is involved in the post-injury inflammatory pathway leading to myocardial tissue remodeling." (PMID 39767568, 2024). "High galectin-3 levels have also been found to be positively correlatedwith advanced congestive heart failure, but negatively correlated with LVEF (R=–0.253; p < 0.001)." (PMID 39077714, 2022). "Galectin-3, a regulatory protein, is elevated in both acute and chronic heart failure and is involved in the inflammatory pathway after injury leading to myocardial tissue remodelling." (PMID 35053194, 2021). "A statistically significant increase was noted of both miR-214 expression and galectin-3 serum concentration in the group with chronic heart failure." (PMID 35053194, 2021). "A positive correlation was demonstrated between miR-214 expression and serum galectin-3 concentration, what suggested the participation of both factors in the development of chronic heart failure." (PMID 35053194, 2021). "In patients with chronic heart failure undergoing CD34+ cell therapy, a decrease in galectin-3 plasma levels is associated with beneficial response to this treatment modality." (PMID 31885743, 2019). "Both ST2 and galectin-3 have shown prognostic value in patients with acute and chronic heart failure on top of natriuretic peptides in general population." (PMID 31435501, 2017).